ITGA1 (integrin subunit alpha 1)
Diseases named in the same sentence as ITGA1 in open-access papers (continued):
Sharing a sentence is not in itself a finding about the gene and the disease.
esophageal cancer (1 paper, 2024). A primary or metastatic malignant neoplasm involving the esophagus. "Genomic loss or deletion of ITGA1/ITGA2 locus was found to be highly frequent in PCa cases and equally prevalent in ovarian and esophageal cancers, suggesting that the tumor suppressor functions of α1‐ and α2‐integrins might not be limited to PCa." (PMID 38169150, 2024).
keloid (1 paper, 2020). An irregularly shaped, elevated mark on the skin caused by deposits of excessive amounts of collagen during wound healing. "The expression of ITGA1 in keloids was three times greater than that in normal skin tissue." (PMID 32182995, 2020).
lymph node metastasis (1 paper, 2015). "SPARC, VCAM1 and ANGPTL4 were found positively correlated with the potentials of lung metastasis, while ITGA1 had a positive relation to lymph node metastasis of enterocoelia." (PMID 26459277, 2015). "Indeed, the protein levels of SPARC, ANGPTL4 and VCAM1 were remarkably correlated with the potentials of lung metastasis, while ITGA1 was positively related to celiac lymph node metastasis (p < 0.01)." (PMID 26459277, 2015).
metastatic tumors (1 paper, 2024). "Next, we examined whether ITGA1/ITGA2 copy loss directly correlates with PCa metastasis in two independent cohorts of PCa patients with primary and metastatic tumors." (PMID 38169150, 2024).
Myocardial fibrosis (1 paper, 2024). "Intriguingly, we found that the proteins displaying strong associations with ITGA1 were significantly enriched in pathways related to myocardial fibrosis." (PMID 38413438, 2024).
neuropathy (1 paper, 2019). A disorder affecting the nervous system that manifests with pain, tingling, numbness, and/or muscle weakness. "A GWAS on oxaliplatin-induced neuropathy implicated genes relating to nerve development and neuron extension (FOXC1 and ITGA1) and pain signaling neurotransmitters (TAC1)." (PMID 30909387, 2019).
oropharyngeal cancers (1 paper, 2020). Carcinoma, predominantly squamous cell, arising from the epithelial cells of the oropharynx. "Indeed, ITGA1 is more expressed in HPV16-positive than HPV16-negative oropharyngeal cancers." (PMID 32813746, 2020).
osteosarcoma (1 paper, 2025). A usually aggressive malignant bone-forming mesenchymal neoplasm, predominantly affecting adolescents and young adults. "Co-IP experiments confirmed the interaction between THBS1 and ITGA1/ITGA6 in the dedifferentiation of osteosarcoma cells." (PMID 40083708, 2025). "In addition, during the sphere formation of osteosarcoma cells, the signal intensity of ITGA1 and ITGA6 on the cell membrane surface at the outer edge of the sphere was higher than that inside the sphere, and colocalization with THBS1 also occurred in cells at the outer edge of the sphere." (PMID 40083708, 2025). "However, the role of THBS1 in promoting osteosarcoma pulmonary metastasis could be reversed by ITGA1 or ITGA6 knockdown." (PMID 40083708, 2025). "Our research has identified the key molecule THBS1, along with its downstream targets ITGA1 and ITGA6, which play a role in the dedifferentiation of osteosarcoma cells." (PMID 40083708, 2025). "Our results also demonstrated that ITGA1 and ITGA6, two subunits of integrin, play a role in mediating extracellular signals in cells and that THBS1 promotes the dedifferentiation and metastasis of osteosarcoma cells." (PMID 40083708, 2025).
overnutrition (1 paper, 2023). An imbalanced nutritional status resulting from excessive intake of nutrients. "Another prioritized candidate gene, ITGA1 (BTA20), encodes a subunit of the cell-surface receptor integrin α1β1, which acts in the regulation of hepatic glucose and lipid metabolism under conditions of overnutrition in vivo." (PMID 37662838, 2023).
podoconiosis (1 paper, 2024). A disease of the lymphatic vessels of the lower extremities that is caused by chronic exposure to irritant soils. "The binding of collagen and laminin in the extracellular matrix through ITGA1 could contribute in the pathology of podoconiosis through enhancing the fibrosis." (PMID 38448477, 2024).
prostate tumors (1 paper, 2024). "The results indicated that ITGA1/ITGA2 were reproducibly found to be downregulated in prostate tumor tissues compared to normal prostate glands." (PMID 38169150, 2024). "We assessed whether the genomic alterations of ITGA1/ITGA2 display any clinical impacts on PCa, and thus investigated potential correlation between ITGA1/ITGA2 copy number loss and their expression levels in human prostate tumors." (PMID 38169150, 2024). "We next investigated the correlation between ITGA1/ITGA2 and YAP1 expression in the human prostate tumors and observed significant positive correlation in multiple independent PCa cohorts." (PMID 38169150, 2024).
pulmonary fibrosis (1 paper, 2023). Chronic progressive interstitial lung disorder characterized by the replacement of the lung tissue by connective tissue, leading to progressive dyspnea, respiratory failure, or right heart failure. "During T-cell mediated inflammation, SEMA7A was shown to mediate its effect through ITGA1/ITGB1 integrin receptor and, during pulmonary fibrosis, through ITGB1 integrin." (PMID 38094294, 2023).
pulmonary hypertension (1 paper, 2020). Increased pressure within the pulmonary circulation due to lung or heart disorder. "In the present study, we also found an increase in ITGA1 in the lung tissue of patients with pulmonary hypertension." (PMID 32030316, 2020).
schwannoma (1 paper, 2025). A benign, usually encapsulated slow growing tumor composed of Schwann cells. "Other notable ECM-related genes include that we identified in our analysis with less evidence in schwannoma included: ITGA1, POSTN, SPP1, ID3, ADAMTS6." (PMID 40585242, 2025).
serous ovarian cystadenocarcinomas (1 paper, 2022). "Amongst the proteomics identified and validated genes, the expression of TGFBI significantly positively correlated with the expression of GFPT2, FLNA, G6PD, ITGAV, ITGA1 and ITGA2 within the serous ovarian cystadenocarcinomas in TIMER database." (PMID 36463238, 2022).
skin tumors (1 paper, 2025). "Conversely, NK inactivation genes including Itga1 (Cd49a), Inpp4b, Tnfsf10, Il7r, and Cxcr6 dramatically decreased in skin tumors." (PMID 40282557, 2025).
tumor (153 papers, 2009 to 2026). "ITGA1 is extensively associated with cancer invasiveness and poor patient prognosis in various tumor types." (PMID 36981021, 2023). "Many over-expressed genes in tumor-associated T cells were involved in tissue remodeling (e.g., Col1a1, Col4a1, Fn1, Lamc1, Mmp2, Mmp10, Timp3) and cell motility/adhesion (Rhoc, Itga1, Itgav)." (PMID 31477729, 2019). "The study revealed that COL4A1/2 plays a critical role in stromal cell differentiation and is significantly enriched at the tumor–stroma interface, where it promotes invasive tumor growth through interactions with ITGA1/B1." (PMID 40867511, 2025). "Four of them had significant expression in immune cells, SLC20A1 with KRT17 was more expressed in malignant tumor cells and ITGA1 was more expressed in mesenchymal cells." (PMID 39127853, 2024). "The results from the present study, in particular, show that CD44 expression was increased in the st-FL tumor along with several members of the CD11a/b family (ITGA1, ITGA5, ITGB1, ITGAV), and all integrins were involved in cellular adhesion and migration." (PMID 39456647, 2024). "Herein, a meta‐analysis of multiple PCa cohorts is performed which revealed that downregulation or genomic loss of ITGA1 and ITGA2 integrin genes is associated with tumor progression and worse prognosis." (PMID 38169150, 2024). "High levels of Itga1 enhanced tumor cell adherence to Col1 and were essential for Col1-induced tumor growth and metastasis." (PMID 34874914, 2022). "We then analyzed the expression profiles of COL1A1, COL4A1, and COL6A2 in TAF and ITGA2, ITGAV, and ITGA1 in tumor cells." (PMID 35322024, 2022). "ITGB1 and ITGA1 were found among the key CAF receptors that mediate crosstalk between tumor cells and CAFs by interacting with COL1A1 and TNC and, thereby, modulating the TME." (PMID 36003785, 2022). "Taken together, these findings suggest that ZEB1 increases tumor cell affinity to Col1 by increasing Itga1 expression." (PMID 34874914, 2022). "Take together, our findings reveal the elevated ITGA1 expression levels in metastatic CRC tumor tissues and sera suggest that the clinical relevance of ITGA1 in CRC metastasis." (PMID 32071551, 2020). "In the present study, our results showed that ITGA1 was up-regulated in tumor tissue and serum of CRC patients, which was significantly associated with the metastatic TNM stages of CRC and circulating CA199." (PMID 32071551, 2020). "Of these, the most significantly upregulated molecule in tumor stroma was a gene product of integrin alpha-1 (ITGA1), and the most upregulated molecule in tumor parenchyma is a product of the CLU gene (i.e., clusterin)." (PMID 29899869, 2018). "Blocking integrin α1 with a therapeutic monoclonal antibody or knocking out ITGA1 in mice both indicated that ITGA1 promoted tumor cell migration and invasion." (PMID 28264467, 2017). "To evaluate the role of ITGA1 during PDAC cell metastasis from a tumor microenvironment that is rich in TGFβ and collagen, we employed the chicken embryo chorioallantoic membrane (CAM) metastasis assay." (PMID 28855593, 2017). "CAV1 and CAV2 were correlated with tumour growth and metastasis, and FN1 was a potential biomarker for some cancers, while ITGA1 and THBS1 were also associated with cancer risk." (PMID 27557147, 2016). "While ITGA1 was decreased (2.11 fold) by baicalein in the H460 tumours, this indicates a common effect of baicalein on integrin alpha expression across a panel of NSCLC cells." (PMID 27586635, 2016). "Notably, the enrichment of collagen and integrin interactions (e.g., COL1A1_ITGA1) further indicates that APOE+ macrophages organize the tumor stroma elements to facilitate tumor progression and immune evasion." (PMID 40303328, 2025). "Although we found that decreased expression of ITGA1, ITGA2, or TEAD1 correlated with PCa severity, it remains unclear whether loss of these three genes have synergistic effects on tumor severity compared with loss of either individual gene." (PMID 38169150, 2024).
tumor (continued). "Interestingly, TEAD1 emerged as the top candidate gene that was co‐expressed with ITGA1/ITGA2 in the TCGA cohort consisting of 498 localized PCa tumor samples." (PMID 38169150, 2024). "Finally, we compared the DEGs between Itgam-expressing and Itga1-expressing tumor NK cells in this human CRC data with our original murine NK cells from MC38 tumors." (PMID 38267402, 2024). "Additionally, we analyzed PCa expression data with clinical features, and found that ITGA1/ITGA2 mRNA levels were significantly lower in tumors with high tumor stage, Gleason score, lymph node and elevated PSA levels in multiple distinct patient cohorts." (PMID 38169150, 2024). "Based on the hub-gene analysis and related studies, we suggested that puerarin may have a prominent effect in inhibiting tumor migration and that this effect is related to the inhibition of ITGA1 expression." (PMID 37694778, 2024). "Known down ITGA1 reduces tumor cell invasion and adhesion in breast cancer." (PMID 39502752, 2024). "This is in consistent with the tumor-promoting role of ITGA1 in these cancers." (PMID 39502752, 2024). "Indeed, ectopic ZEB1 expression promoted 393P tumor growth and metastasis, and Itga1 depletion abrogated ZEB1-induced cell proliferation on Col1-coated wells without affecting cell proliferation on plastic." (PMID 34874914, 2022). "Itga1 mediates collagen-induced tumor growth and metastasis." (PMID 34874914, 2022). "Similar to the MMPs motif, these ITGA1–collagen interactions may also involve tumor microenvironment and effect cellular behaviors and signal transduction pathways in NSCLC." (PMID 33669233, 2021). "After adjustment by tumor purity, we found ITGA1/A5/A8/A11/AD/AV and ITGB1 showed weakly correlation with macrophage markers in OC, ITGA5/A11 and ITGB5 weakly correlated with Treg markers, ITGAD and ITGB6 showed weakly correlation with natural killer cells markers." (PMID 32765584, 2020). "Interestingly, the sizes of tumor derived from normal colonic epithelial NCM460 cells with overexpressing ITGA1 were significantly increased compare to the cells infected with LV-NC control group (p<0.01)." (PMID 32071551, 2020). "Moreover, the significantly upregulated DEPs (ITGA1, ITGA6, and ITGB4) that were associated with tumor invasiveness and aggressiveness were confirmed by immunoaffinity analysis in FSH-positive vs. negative NFPAs." (PMID 31832114, 2019). "Indeed, integrins gene expression in the clinical ESCC tumor tissues show significant higher levels of integrin α-1 (ITGA1), ITGA2, ITGA5 and ITGB1 mRNA compared to normal tissue from the same patient." (PMID 30241395, 2018). "Thus, targeting ITGA1 in this context has significant potential to reduce systemic tumor burden and improve patient survival." (PMID 28855593, 2017). "Although more study is needed to explain the presence of fewer vessels in the tumors, one may speculate that the reduction in these tumor-derived endothelial cells is related to the integrin α1 subunit/ITGA1 repression in the parental tumor cells." (PMID 28933766, 2017). "Many reports showed that ITGA1 may play an important role on migration and invasion in various tumor." (PMID 28264467, 2017). "Therefore, our work has deciphered a novel mechanism by which TEAD1 regulates α1‐ and α2‐integrin expression and thereby exerts tumor suppressive functions while loss of TEAD1 and/or ITGA1/ITGA2 in PCa genomes were found to correlate with disease progression and aggressiveness." (PMID 38169150, 2024). "The results constantly showed that PCa patients with triple low expression of ITGA1, ITGA2 and TEAD1 demonstrated higher Gleason score, PSA levels, advanced tumor stages and lymph node metastasis." (PMID 38169150, 2024).
tumor (continued). "Taken together, these results demonstrate prognostic values of ITGA1/ITGA2 loss/del and downregulation upon PCa progression to metastatic stage, suggesting that ITGA1/ITGA2 are new biomarkers that could distinguish aggressive disease and might possess tumor suppressive functions in PCa development." (PMID 38169150, 2024). "Many signals favoring tumor cells were significantly activated in C2, such as integrin-related signals (COL9A3 − (ITGA2+ITGB1), JAM3 − (ITGAM+ITGB2), COL6A1 − (ITGA1+ITGB1)), immune suppression signals (CD99 − PILRA), etc.." (PMID 39391717, 2024). "The results showed that ITGA1, ITGB1, ITGB8 and SDC1 were highly expressed in tumor cells when compared with control group." (PMID 38526745, 2024). "To confirm the potential function of ITGA1 in tumor immunity, we performed the ESTIMATE methods to analyze the relation between ITGA1 and immunological infiltration based on TCGA dataset." (PMID 39502752, 2024). "Among stromal fibroblast cells, ITGAV, ITGA1, ITGB1, and ITGB5 were significantly upregulated following IO and, notably, isolated tumor cells found in the stroma showed upregulation of B2M, VIM, ITGA5, ITGB2, and ITGA3." (PMID 39639369, 2024). "• A functional antitumor response, intra-tumor cell retention (ITGAE, ITGA1, etc.) and tumor residency (ALOX5AP, CXCL13, etc.) similar to CD39+CD8+T cells.• Expressed activation/co-stimulation genes to resist exhaustion." (PMID 36451828, 2022). "Therefore, the effect of ITGA1 in tumor immune therapy may need further verification." (PMID 34660316, 2021). "ITGA1 dimerizes with ITGB1 to bind collagens I, IV, VI, and fibrillar collagens, making it an excellent candidate to affect tumor cell adhesion to the peritoneum." (PMID 32525899, 2020). "We observed the ITGA1/A2/A4/A5/A7/A8/A11/A2B/AL/ AM/AV/AX and ITGB1/B2/B3/B5/B6/B7 showed significantly obvious correlation with tumor purity in OC." (PMID 32765584, 2020). "We found that the ITGA1 protein was significantly higher in human CRC tissues and cell lines than both paired non-tumor tissues and normal cells, respectively." (PMID 32071551, 2020). "The presence of extensive necrosis in sh-ITGA1 derived tumors, which is often at the center of the tumors, suggests that this necrosis is secondary to the reduction in vascularization of these tumors as observed herein, which could be related to integrin α1 subunit/ITGA1 repression in tumor cells." (PMID 28933766, 2017). "BIRC3, CAV1, CAV2, FN1, ITGA1 and THBS1 were functionally enriched to focal adhesion, which contributes to antiangiogenic and anti-tumour effects." (PMID 27557147, 2016). "Additionally, tumor adhesion and metastasis-promoting molecules, including ITGB4 and ITGB8, whereas ITGA1 and ITGA2 were downregulated in ST6GAL1-knockdown cells." (PMID 39937175, 2025). "Additionally, azvudine regulated the interactions from other tumor immune cells to CD4+ T and CD8+ T cells through ligand‒receptor pairs such as COL1A2‒(ITGA1 + ITGB1), CCL4‒CCR5, CCL6‒CCR2, and CXCL16‒CXCR6." (PMID 39819859, 2025). "Notably, we observed increased expression of tissue-residence markers (ITGA1, VIM, LGALS1) also in proliferating blood NKs, indicating their inclination toward blood-tumor migration." (PMID 40164596, 2025). "Integrin α1 (ITGA1), a family member of integrins, is involved in regulating intercellular signaling transduction by binding with the extracellular matrix (ECM) and thus plays a crucial role in the proliferation of tumor cells, and migration." (PMID 39502752, 2024). "IHC results showed that ITGA1 protein was aberrantly expressed in CRC tumor tissues, but not in matched adjacent non-cancerous tissues." (PMID 32071551, 2020). "Together with our results demonstrating that ITGA1 inhibition sensitizes PDAC cells to gemcitabine-induced cytotoxicity, ITGA1 represents a key new target for sensitizing both primary and metastatic tumor cells to currently available therapeutic strategies." (PMID 28855593, 2017).